VPS4B (vacuolar protein sorting 4 homolog B)
Diseases named in the same sentence as VPS4B in open-access papers (continued):
Sharing a sentence is not in itself a finding about the gene and the disease.
tumor (continued). "Instead, we provide evidence that impaired autophagy leads to reduced granzyme B clearance, suggesting that Vps4b or Atg5 depletion facilitates tumor cell lysis by CD8+ T cells through enhanced granzyme B accumulation." (PMID 35379808, 2022). "It is reported that VPS4B serves as a tumor suppressor in breast cancer via promoting the degradation of epidermal growth factor receptor." (PMID 29575674, 2019). "Overall, Hrs (ESCRT-0) and Tsg101 (ESCRT-I) seem to be mostly up- and Vps37A (ESCRT-I), Chmp1A and Vps4B mostly down-regulated in tumor samples." (PMID 24641493, 2014). "Hypoxic conditions, frequently found in the center of larger tumor entities, induced a down-regulation of Vps4B by the ubiquitin proteasome system." (PMID 24641493, 2014). "They confirmed that suppression of VPS4A in VPS4B-deficient cells leads to selective accumulation of ESCRT-III filaments, resulting in cytokinesis defects, nuclear deformation, G2/M arrest, apoptosis, and significant tumor regression." (PMID 37404768, 2023). "While remaining Cas9 expression in these lines did not affect tumor growth, loss of Rnf31 and Vps4b markedly decreased tumor mass and resulted in significantly enhanced survival of tumor-bearing mice." (PMID 35379808, 2022). "Moreover, our study revealed that upon concomitant depletion of VPS4A and VPS4B proteins, dying cancer cells secreted immunomodulatory molecules that mediated inflammatory and anti‐tumor responses." (PMID 31930723, 2020). "Finally, we showed that the synthetic lethality between VPS4A and VPS4B is conserved across tumor types (CRC, lung, pancreas) and species (Fig EV5)." (PMID 31930723, 2020). "Thus, we confirmed that depleting VPS4A protein in CRC cells with compromised VPS4B expression inhibits tumor growth in mouse xenografts." (PMID 31930723, 2020). "The VPS4B gene is widely expressed in the human body, including pulp tissue, and has been found to be a tumor suppressor gene that can regulate tumor progression." (PMID 29575674, 2019). "However, as T cell immunity is generally dependent on sufficient tumor antigenicity, future studies should determine whether Rnf31 and Vps4b depletion will show similar phenotypes in other PDA tumor models." (PMID 35379808, 2022). "Therefore, we predict that the dependency on VPS4A will occur across many VPS4B‐deficient cells within the tumor mass, irrespective of their genetic background." (PMID 31930723, 2020). "Based on these data, we conclude that CRC‐associated downregulation of VPS4B does not reflect its own tumor suppressor function but rather represents a passenger alteration co‐existing with concomitant loss of the neighboring 18q‐located tumor suppressors, such as DCC, SMAD2, and SMAD4." (PMID 31930723, 2020). "We identified Rnf31 and Vps4b in our in vitro and in vivo CRISPR screens using the OVA/OT-I tumor model, which ensured sufficient antigenicity of tumor cells." (PMID 35379808, 2022). "For Vps4b we find that inactivation impairs autophagy, resulting in increased accumulation of CD8+ T cell-derived granzyme B and subsequent tumor cell lysis." (PMID 35379808, 2022). "Among these genes, only DYRK1A, VPS4B, PLAGL2, these three genes have been reported to act as tumor-promoter in HCC." (PMID 33596983, 2021). "Based on this finding, we suggest that most VPS4B‐deficient cancer cells would not avert cell death upon therapeutic VPS4A perturbation, irrespective of their individual genetic or epigenetic alterations in one or more death pathways that may appear in a heterogenic tumor mass." (PMID 31930723, 2020).
cancer (12 papers, 2013 to 2025). A tumor composed of atypical neoplastic, often pleomorphic cells that invade other tissues. "Humans have 2 VPS4 paralogs, VPS4A and VPS4B, and the loss of either paralog has been identified in a significant proportion of cancers, rendering them dependent on the remaining paralog for survival." (PMID 40147096, 2025). "Nevertheless, depleting VPS4A in cancer cells with loss of VPS4B led to synthetic cell death, suggesting at least partial overlap between these isoforms." (PMID 38687820, 2024). "VPS4A is essential in cancers harboring loss of VPS4B adjacent to SMAD4 on chromosome 18q and VPS4B is required in tumors with co-deletion of VPS4A and CDH1 (E-cadherin) on chromosome 16q." (PMID 37404768, 2023). "The expression levels of VPS4B in different types of cancer have been shown to be associated with varying clinical and pathological factors, as well as with patient survival outcomes." (PMID 37404768, 2023). "Altogether, our analysis of TCGA databases revealed that the VPS4B allele is frequently lost in many cancer types, prominently in CRC." (PMID 31930723, 2020). "Our results identify a novel pair of druggable targets for personalized oncology and provide a rationale to develop VPS4 inhibitors for precision therapy of VPS4B‐deficient cancers." (PMID 31930723, 2020). "In summary, our findings establish a foundation for future work aiming to develop a VPS4 inhibitor as a putative therapeutic for precision therapy of VPS4B‐deficient cancers, such as CRC." (PMID 31930723, 2020). "Our results identify a pair of novel druggable targets for personalized oncology and provide a rationale to develop VPS4 inhibitors for precision therapy of VPS4B‐deficient cancers." (PMID 31930723, 2020). "This study highlights the possibility of using synthetic lethality between these paralogs for treatment of VPS4B‐deficient cancers." (PMID 31930723, 2020). "Here, by demonstrating the synthetic lethal interaction between two ubiquitously expressed human paralogs VPS4A and VPS4B, we uncovered a novel therapeutic target to treat patients bearing VPS4B‐deficient cancers, for example, CRC used as a model in our study." (PMID 31930723, 2020). "However, while the deletion of VPS4B has been linked to cancer mostly indirectly due to its location on chromosome 18, specific heterozygous point mutations in VPS4A were sufficient to induce severe pathologies." (PMID 38687820, 2024). "Moreover, in the course of revision of this manuscript, thanks to the new dataset deposited in the DepMap portal, we verified that even a partial loss of VPS4B expression renders cancer cells more vulnerable to VPS4A perturbation." (PMID 31930723, 2020). "Currently, we are exploring whether this attenuation of the glycolytic pathway by VPS4B could also lead to the reduction of lactate-induced acidosis that is commonly associated with many cancers." (PMID 23431444, 2013). "Since mitochondria are known to be degraded by autophagy, we postulate that the VPS4B-autophagy-mediated mitochondrial degradation could be impaired during the premetastatic stage of cancer or in VPS4B-depleted cells and ultimately causes the activation of mitochondrial fatty acid β-oxidation." (PMID 23431444, 2013). "Second, while VPS4A was reported to function as a tumor suppressor, VPS4B exhibited pro- or anti-oncogenic activities in different cancers." (PMID 38687820, 2024). "In summary, there exists “synthetic lethality” of the VPS4A gene and VPS4B gene in cancer, especially in CRCs." (PMID 37404768, 2023). "The overview of Pan‐Cancer TCGA somatic copy number alteration dataset revealed about a 30% incidence of chromosome 18q LOH at the VPS4B locus." (PMID 31930723, 2020). "To study the extent of genetic changes at the VPS4B locus in different types of cancer, we mined The Cancer Genome Atlas (TCGA)." (PMID 31930723, 2020). "By exploring TCGA datasets, we found here that the VPS4B gene undergoes deletion as a part of 18q in many cancer types." (PMID 31930723, 2020).
cancer (continued). "Further analysis of individual cancer datasets showed frequent VPS4B deletion in several types of cancer with CRC being the most affected." (PMID 31930723, 2020). "To confirm the synthetic lethality between VPS4A and VPS4B, we wished to use a non‐engineered cancer cell line with low VPS4B expression." (PMID 31930723, 2020). "VPS4B is located at 18q21 and is frequently deleted with the tumour suppressor SMAD4, explaining the relatively high frequency of loss of VPS4B in cancer." (PMID 32463358, 2020). "This genetic alteration correlates with decreased VPS4B mRNA and protein content in cancer tissues that we demonstrated using our collections of CRC patient samples." (PMID 31930723, 2020). "In most cases (57%), we observed a slightly decreased VPS4B staining in cancer samples (very intense in normal colon versus medium intense in CRC; 3+→2+)." (PMID 31930723, 2020). "Moreover, cancer cells with low expression of VPS4B are sensitized to depletion of VPS4A." (PMID 31930723, 2020). "Although obtaining a specific VPS4A inhibitor may be infeasible (due to the high identity between paralogs), a pan‐VPS4 inhibitor could still be useful, because VPS4B‐deficient cancer cells are likely more sensitive to VPS4 inhibition than normal cells." (PMID 31930723, 2020). "SIGNIFICANCE STATEMENT: VPS4A and VPS4B, paralogs of the AAA-ATPase VPS4, are critical for cancer cell survival." (PMID 40147096, 2025). "Recent attempts to develop inhibitors for VCP/p97 (a distinct member of the type II AAA+ ATPase family, overexpressed in many cancers) identified two compounds that inhibit yeast VPS4 and human VPS4B." (PMID 31930723, 2020). "Our current study indicated that the glycolytic pathway is downregulated in VPS4B-depleted SKBR3 cells, suggesting a potential cross-talk between the abnormal glycolysis in cancer and MVB dysfunction." (PMID 23431444, 2013). "Furthermore, by leveraging the identification of similar cancer cell lines, we uncovered a potential gene pair, VPS4A and VPS4B, with therapeutic implications." (PMID 39435285, 2024). "For non-cancer studies, the miDRB-targeted exosome biogenesis genes for ferroptosis-inhibiting miRNAs are retrieved as follows: miR-19a-3p (SDC1, VPS4B, and MYO5B), miR-424-5p (VPS4A and MYO5B), miR-4291 (ATP9A, SMPD3, TSG101, and MYO5B), miR-522-3p (PDCD6IP), and miR-670-3p (CD34 and RAB27A)." (PMID 38892270, 2024). "When analyzing the tissue microarrays, we found that the staining of VPS4B protein from analyzed pairs of matched cancer patient samples was not as intense as in normal colon (3+→3+)." (PMID 31930723, 2020). "Furthermore, alternative and/or mis-splicing of ESCRT genes that affect autophagy play roles in the pathogenesis of several diseases, including TSG101 in cancer and CHMP2B and VPS4B mis-splicing in the pathogenesis of FLTD and dental dysplasia I (respectively)." (PMID 34440370, 2021). "Most significantly, our results show that VPS4B downregulation decreased the expression of FASN by simultaneously decreasing its rates of synthesis and increasing the rate of its degradation, suggesting that both de novo fatty acid synthesis and fatty acid β-oxidation are tightly coupled in cancer." (PMID 23431444, 2013). "While VPS4B depletion did not perturb autophagy in human cells, in the future it would be interesting to test whether autophagy inhibition also leads to elevated granzyme B accumulation in human cancers." (PMID 35379808, 2022).
infection (9 papers, 2011 to 2025). The state of being infected such as from the introduction of a foreign agent such as serum, vaccine, antigenic substance or organism. "However by 9 h post-infection the interaction appears to have been lost, suggesting that the interaction between L1 and VPS4B occurs relatively early during the infectious entry of HPV-16 PsVs." (PMID 28349933, 2017). "This infection protocol was chosen to ensure that we were examining virus that was produced in cells expressing the induced VPS4B proteins, while minimizing the effect that these proteins could exert on viral entry." (PMID 27010636, 2016). "We next examined the levels of HCV Core and the infectivity of HCV in the culture supernatants as well as the level of HCV RNA in the TSG101, Alix, Vps4B, or CHMP4b stable knockdown RSc cells 97 h after HCV-JFH1 infection at an MOI of 0.1." (PMID 21264300, 2011). "However, silencing of TSG101, CHMP3, VPS4B, or ALIX—components of the ESCRT pathway that control MVB biogenesis—has been shown to impair the infection and entry of CCHFV, indicating that ESCRT plays a role in CCHFV entry." (PMID 40996032, 2025). "To further investigate whether MVB biogenesis is critical for CCHFV infection, we tested the effect of depleting cellular Tsg101, Vps24 (ESCRT-III component), Vps4B, and Alix/Aip1 on efficiency of CCHFV-mKate2 infection." (PMID 25233119, 2014).
VPS4B also shares sentences with these, for which no sentence is quoted: melanoma (2 papers); adenocarcinoma (1); candidiasis (1); colon adenocarcinoma (1); cryptococcosis (1); dentin dysplasia (1); fungal infection (1); liver fibrosis (1); osteoarthritis (1); ovarian serous cystadenocarcinoma (1); parasite infection (1); Parkinson disease (1); prostate carcinoma (1); rectum adenocarcinoma (1); testicular germ cell tumor (1); Wilms tumor (1).